GGTLC3 (gamma-glutamyltransferase light chain family member 3)
Description:
Likely to be catalytically inactive.
Synonyms: GGT
Tractability: No criterion of Open Targets' tractability assessment is met for any kind of drug.
Gene: Protein-coding gene on chromosome 22 (18,516,338 to 18,518,161, reverse strand). Ensembl gene ENSG00000274252.
Gene Ontology:
Molecular function: glutathione hydrolase activity
Biological process: leukotriene D4 biosynthetic process; glutathione catabolic process
Cellular component: extracellular exosome
Homologues: Orthologues: macaque GGT1 (90% identical), dog GGT1 (81% identical), rat Ggt1 (77% identical), mouse Ggt1 (75% identical), zebrafish ggt1a (60% identical), zebrafish ggt1b (53% identical), zebrafish ggt1l2.2 (44% identical), zebrafish ggt1l2.1 (43% identical), zebrafish si:dkey-222h21.12 (42% identical), zebrafish si:ch73-236c18.3 (41% identical), Drosophila melanogaster Ggt-1 (40% identical), tropical clawed frog ggt1 (39% identical), and 2 more. Paralogues in human: GGT1 (93% identical), GGTLC1 (89% identical), GGTLC2 (84% identical), GGT5 (38% identical), GGT7 (27% identical), GGT6 (14% identical).
Diseases named in the same sentence as GGTLC3 in open-access papers:
GGTLC3 is named in the same sentence as 1 disease in open-access papers, as found by Europe PMC text mining. Sharing a sentence is not in itself a finding about the gene and the disease.
GGTLC3 shares sentences with these, for which no sentence is quoted: lung carcinoma (1 paper).